PTCH1 (patched 1)
Diseases named in the same sentence as PTCH1 in open-access papers (continued):
Sharing a sentence is not in itself a finding about the gene and the disease.
medulloblastoma (continued). "Furthermore, PTCH1, DDX3X and SMO driver mutations characteristic to SHH medulloblastomas, and PRDM6 enhancer hijacking driver events found in Group 4-medulloblastomas associated with MuAt features (FDR<1%)." (PMID 37420249, 2023). "Similar to Ptch1+/–mice (medulloblastoma model) and Eker rats (renal cancer model), some Unidentified tumors in ApcMin/+ mice could not be identified by sequence analysis." (PMID 37824459, 2023). "Moreover, the overproliferation of granule cell precursors leading to medulloblastoma has been reported in mice with homozygous or heterozygous deletions in Ptch1, the mouse ortholog of PTCH1." (PMID 35328080, 2022). "Importantly, the absence of medulloblastoma in teratomas generated from gene-edited PTCH1+/+ iPSCs confirmed the idea that PTCH1 is indeed a driver gene in the formation of medulloblastomas observed in our study." (PMID 35618979, 2022). "WES detected an important PTCH1 germline variant in patient P46 with an SHH-activated medulloblastoma, which is not covered by the TSO500." (PMID 35475276, 2022). "Mutations resulting in overactivation and/or deregulation of Shh signaling, including loss of patched 1 (Ptch1), alter the development of CGNP, making them hyperproliferative and susceptible to malignant transformation into medulloblastoma (MB), the most common malignant pediatric brain tumor." (PMID 35040952, 2022). "PTCH1 LOH has been associated with enhanced medulloblastoma formation as a result of increased SMO and GLI activation, and the loss of GLI1 markedly suppressed spontaneous medulloblastoma formation in Ptc1+/− mice." (PMID 34572373, 2021). "(b) Ligand-independent model: Clinical observations have found mutations of PTCH-1 and PTCH-2 in basal cell carcinomas and in medulloblastomas, resulting in dysregulated GLI signaling due to ineffective sequestration of SMO signaling, regardless of SHh ligand levels." (PMID 34113570, 2021). "This may be immediately evident for tumors such as medulloblastomas and basal cell carcinomas that frequently show mutations in either SMO or PTCH1 genes." (PMID 34638386, 2021). "Interestingly, two additional dysmorphic Gorlin patients in our cohort – one harboring a PTCH1 and the other a SUFU mutation - presented with developmental delay prior to the diagnosis of the medulloblastoma/the beginning of treatment." (PMID 34888241, 2021). "There are currently no direct estimates of the incidence of SUFU and PTCH1 PV carriers in the general population and no unbiased estimates of the risk of childhood medulloblastoma for each condition." (PMID 33860896, 2021). "Mutations in PTCH1 and SMO, although to a lesser degree than BCC, have also been detected in other cancers such as medulloblastoma, mesothelioma, cervical cancer, breast cancer, odontogenic keratocystic tumors, acute lymphoblastic leukemia, and hepatocellular carcinoma (HCC)." (PMID 34572373, 2021). "Following successful identification in the Ptch1 conditional model, we aim to determine if similar expression profiles can be observed in human medulloblastoma subgroups, with the intent of identifying novel CD antibody markers to further profile human medulloblastoma." (PMID 30657775, 2019). "We next investigated whether co-labelling of CD15 and CD24 could further purify a TIC cell population in Ptch1 deleted medulloblastoma." (PMID 30657775, 2019).
medulloblastoma (continued). "Next, we explored if NES cells with mutant PTCH1 would generate medulloblastoma." (PMID 31204176, 2019). "Analogously, ∼15% of Ptch1+/− transgenic mice also develop medulloblastoma." (PMID 31204176, 2019). "Based on these findings, we hypothesised that CD15 alone was not sufficient to purify the putative tumour-initiating granule cell precursor population within Ptch1 deleted medulloblastoma." (PMID 30657775, 2019). "Interestingly, Ptch1 deletion in precursors of GNP cells located in the ventricular zone of the dorsal hindbrain also initiated medulloblastoma." (PMID 31204176, 2019). "Co-labelling with CD15 and CD24 allowed for the identification of a more mitotic and tumorigenic CD15+/CD24+ cell population within Ptch1 deleted medulloblastoma, illustrating that the CD24 TIC population could be further purified with CD15." (PMID 30657775, 2019). "To identify TIC markers in medulloblastoma we utilised the Ptch1 conditional mouse model." (PMID 30657775, 2019). "In addition to syndromic diseases, PTCH1 mutations have been implicated in several cancers including sporadic basal cell carcinoma (BCC), squamous cell carcinoma, medulloblastoma, and embryonal rhabdomyosarcoma." (PMID 31362756, 2019). "Similar to Gli1/2 RNAi, Kapβ2 knockdown in SmoM2-induced medulloblastoma cells diminished the expression of Shh target genes, including Gli1, Ptch1, CycD1, and N-Myc, leading to growth inhibition of the medulloblastoma cells as indicated by a cell survival assay." (PMID 28777795, 2017). "Importantly, the level of CHOP was strongly increased in medulloblastoma in Ptch1+/−; Gadd34−/− mice compared to Ptch1+/−; Gadd34+/+ mice, suggesting that GADD34 homozygous mutation strongly elevates the ISR in medulloblastoma in Ptch1+/− mice." (PMID 27802424, 2016). "We determined the effects of the enhanced ISR on medulloblastoma in adult Ptch1+/− mice." (PMID 27802424, 2016). "Bromodeoxyuridine (BrdU) labeling and proliferating cell nuclear antigen (PCNA) IHC (data not shown) showed that GADD34 mutation, either heterozygous or homozygous, did not significantly affect the number of proliferating cells in medulloblastoma in Ptch1+/− mice." (PMID 27802424, 2016). "We also showed that GADD34 is upregulated in medulloblastoma in Ptch1+/− mice." (PMID 27802424, 2016). "Immunohistochemistry (IHC) for glial fibrillary acidic protein (GFAP) and synaptophysin showed that the expression pattern of both GFAP and synaptophysin in medulloblastoma in both Ptch1+/−; Gadd34+/− mice and Ptch1+/−;Gadd34−/− mice was comparable with Ptch1+/−; Gadd34+/+ mice." (PMID 27802424, 2016). "Importantly, our previous study showed that PERK haploinsufficiency reduces the incidence of medulloblastoma in Ptch1+/− mice." (PMID 27802424, 2016). "We showed here that GADD34 homozygous mutation strongly increased the expression of CHOP in medulloblastoma but did not affect tumor cell apoptosis in adult Ptch1+/− mice." (PMID 27802424, 2016). "Nevertheless, neither GADD34 heterozygous mutation nor GADD34 homozygous mutation had a significant effect on medulloblastoma cells in adult Ptch1+/− mice." (PMID 27802424, 2016). "Moreover, gross examination and H&E staining revealed that 4 out of 55 asymptomatic Ptch1+/−; Gadd34−/− mice developed medulloblastoma." (PMID 27802424, 2016). "In accordance with this previous study, we showed here that the moderately enhanced ISR via GADD34 heterozygous mutation slightly increased the number of hyperplastic lesions in young Ptch1+/− mice and noticeably increased the incidence of medulloblastoma in Ptch1+/− mice." (PMID 27802424, 2016). "Ptch1+/− mice develop symptomatic medulloblastoma typically between the ages of 2 and 8 months." (PMID 27802424, 2016). "The development of medulloblastoma in Ptch1+/− mice exhibits distinct steps of progression." (PMID 27802424, 2016).
medulloblastoma (continued). "In fact, one remarkable feature of radio-induced medulloblastoma in Ptch1+/− mice is the development through microscopically recognizable preneoplastic lesions (PNLs), ranging from small areas of hyperproliferation of granule neurons to overt nodules, and finally to microtumors." (PMID 26452034, 2015). "The LOH analysis of tumor DNA showed Ptch1 biallelic loss in all tumor samples, suggesting that mechanisms other than interstitial deletions, typical of radiation-induced medulloblastoma, did not account for the observed increased cancer risk." (PMID 26452034, 2015). "We found that Dicer restricts SHH medulloblastoma development in Ptch1+/- mice." (PMID 26091048, 2015). "Cyclopamine also suppresses medulloblastoma development in Ptch1+/− mice." (PMID 26512695, 2015). "Ligand-independent constitutive activation of Hh pathway in cancers is characterized by somatic mutations in Ptch1, Smo, or Sufu, consequently increasing Hh pathway activity and leading to a higher incidence of basal cellular carcinoma (BCC) and medulloblastoma." (PMID 26296751, 2015). "Natural selection due to the high incidence of lethal medulloblastoma might have decreased the SUFU-mutant pedigrees more than the Ptch1-mutant pedigrees." (PMID 23951062, 2013). "Finally, this advances medulloblastoma development in Ptch1+/− Nos2−/− mice compared to Ptch1+/− Nos2+/+ mice." (PMID 22438824, 2012). "However, high levels of GLI1 correlated with high levels of Cyclin D2 and PTCH1 in medulloblastoma cell lines and tumor samples." (PMID 21059263, 2010). "In addition, inactivating mutations of PTCH1 and SUFU and activating mutations of SMOH account, in total, for at least 20% of all cases of medulloblastoma in humans." (PMID 20520772, 2010). "A second subtype, not completely separated from all other medulloblastomas in their cluster analyses, was found to be enriched in mutations in either PTCH1 or SUFU and was characterized by activation of the SHH signaling pathway." (PMID 18769486, 2008). "Interestingly, recent studies have shown that CUR inhibits the Hh pathway in several other cancers, such as breast cancer, gastric cancer, and medulloblastoma, by downregulating the expression of SHh, PTCH1, and GLI1/GLI2, leading to reduced cell proliferation, invasion, and migration." (PMID 39457084, 2024). "Adult SHH-activated medulloblastomas display a higher mutation burden compared to their pediatric counterparts, particularly with mutations associated with the SHH pathway, mainly Patched1 (PTCH1) and Smoothened (SMO), as well as mutations in CREB binding protein (CREBBP), BRPF1, and TERT promoter." (PMID 37568705, 2023). "In contrast, no medulloblastoma-like tissue positive for medulloblastoma markers was observed in teratomas generated from gene-edited PTCH1+/+ iPSCs, demonstrating that the rescuing a mutated allele in PTCH1+/− iPSCs inhibited medulloblastoma formation." (PMID 35618979, 2022). "In addition, medulloblastoma-like tissues were frequently observed in PTCH1−/− teratomas." (PMID 35618979, 2022). "Looking at those patients who presented with an SHH activated medulloblastoma aged 3.5 years and younger as well as assuming SHH activation for all our Gorlin patients, approximately 17% of them would have tested positive for a pathogenic PTCH1 or SUFU mutation." (PMID 34888241, 2021). "This would suggest that our high frequency MB mouse model Ptch1+/−/Tis21KO, carrying activation of both the Shh and the PI3K/AKT/mTOR pathways, could be a model representative of such a cohort of patients with high-risk Shh-type medulloblastoma." (PMID 34395258, 2021).
medulloblastoma (continued). "In our study, 20% of patients had medulloblastoma, but no PTCH1 pathogenic variants were detected." (PMID 33441926, 2021). "Similarly, approximately 15% of Ptch1 +/− transgenic mice develop medulloblastomas." (PMID 33066274, 2020). "Indeed, all Ptch1-KO mice are affected by clinically evident medulloblastoma between 10–12 weeks, while a certain variability in frequency and age of onset, dependent on the copy number of the transgene and on the genetic background, characterize the SmoA1 model." (PMID 31873117, 2019). "Additionally, GADD34 mutation, either heterozygous or homozygous, did not affect medulloblastoma cells in adult Ptch1+/− mice." (PMID 27802424, 2016). "Interestingly, neither GADD34 heterozygous mutation nor GADD34 homozygous mutation had an effect on medulloblastoma cells in adult Ptch1+/− mice." (PMID 27802424, 2016). "Patched1 heterozygous (Ptch1+/−) mice, characterized by aberrant activation of the Sonic hedgehog (Shh) signaling pathway, are a well-known murine model of spontaneous and radiation-induced medulloblastoma (MB), a common pediatric brain tumor originating from neural granule cell progenitors (GCPs)." (PMID 27626168, 2016). "Its role in cancer was first revealed when the linkage of the human patched 1 (PTCH1) gene was established with the basal cell nevus syndrome (BCNS or Gorlin syndrome), a rare hereditary disorder characterized by multiple basal cell carcinomas (BCC) and predisposition to medulloblastomas." (PMID 23349881, 2013). "In various cancer models—breast cancer cells, gastric cancer cells, medulloblastoma —CUR has been shown to inhibit the Hh pathway by downregulating the expression of SHh, PTCH1, and GLI1/GLI2." (PMID 39457084, 2024). "For instance, parents of neonates with a GPR161 variant can be reassured that absolute risks of medulloblastoma are very small and the increased risk may disappear after age 4 years (this will be reassuring if results are given for a 5year old) similar to SUFU and PTCH1." (PMID 36961676, 2023). "Since PTCH1−/− iPSCs are one step closer to tumor formation according to the Knudson’s two-hit hypothesis, these gene-edited iPSCs may be a good model for the formation of medulloblastoma in NBCCS and may also be useful for drug screening to identify personalized treatments for this tumor type." (PMID 35618979, 2022). "Considering the high incidence of PTCH1 and SUFU PVs in medulloblastomas, and in particular SHH-MBs in young children, experts recommend a germline PTCH1 and SUFU PVs screening for all children with SHH-MB, especially those diagnosed before the age of 5." (PMID 33860896, 2021). "SHH-activated medulloblastoma is highly heterogeneous and many key molecules in the SHH signaling pathway such as SUFU, smoothened (SMO), PTCH1, GLI1 and GLI2 have been dysregulated in this subgroup." (PMID 33869004, 2021). "Mice heterozygous for Patched1 (Ptch1+/−), a SHH receptor, are regarded as the best animal model to study the SHH subgroup of medulloblastoma." (PMID 27802424, 2016). "Downregulation of DNMT1 expression has been shown to reduce tumor incidence in the Ptch1 heterozygous knock-out mice, a mouse model of SHH subgroup medulloblastomas." (PMID 26097868, 2015). "In this study, we sought to understand the regulatory roles of GLI1, the immediate downstream activator of the Shh signaling pathway on its downstream target genes PTCH1, Cyclin D2, Plakoglobin, NKX2.2 and PAX6 in medulloblastoma and astrocytic tumors." (PMID 21059263, 2010). "In the course of our studies, we sought to understand the regulation of certain downstream target genes of the Shh pathway, including PTCH1, Cyclin D2, Plakoglobin, NKX2.2, and PAX6, in a panel of medulloblastoma and astrocytoma cell lines and tumors." (PMID 21059263, 2010).
medulloblastoma (continued). "Similarly, chromosome 9 and 10, commonly deleted in these cancers, contain several important suppressor genes such as CDKN2A and PTEN in glioma; XPA, PPP6C, and CDKNA in melanoma; PTCH1 and SUFU in medulloblastoma." (PMID 41537310, 2026). "Upon long-term treatment with LDE225, the RNA levels of the known SHH pathway genes Ptch1, Smo, Gli1, and Gli2 were equivalent to those in control-treated tumors in SD-CSC medulloblastomas, indicating continued activation of the SHH pathway consistent with acquired mutations in this pathway." (PMID 36688010, 2022). "However, just over 200 of the Waszak series were over 18 years of age, thus 11/800 (1.4%) of childhood medulloblastoma had a SUFU PV and 9/800 (1.1%) had a PTCH1 PV." (PMID 33860896, 2021). "CD117 has previously been shown to not label Ptch1 deleted murine medulloblastoma but we wanted to investigate its potential as a marker in Ptch1lox/lox;GFAPcre medulloblastoma." (PMID 30657775, 2019). "CD15 and CD133 expression have been identified on TICs within murine Ptch1 deleted medulloblastoma, but until now CD24 expression had not been extensively investigated in any murine model of medulloblastoma." (PMID 30657775, 2019). "We showed that GADD34 mutation, either heterozygous or homozygous, elevated the level of CHOP but did not change the level of p-eIF2α in medulloblastoma in adult Ptch1+/− mice." (PMID 27802424, 2016). "It is likely that the low incidence of medulloblastoma in Ptch1+/− mice (30.3%) is responsible for the statistically non-significant result." (PMID 27802424, 2016). "Using whole-genome sequencing (WGS) we characterized the medulloblastoma-driving Ptch1 deletions in detail and show that no off-targets were detected in these tumours." (PMID 26067104, 2015). "Whole-body X-irradiation of radiosensitive Ptch1+/- mice, with the upper half of the animals shielded, resulted in the induction of medulloblastoma, depicting the non-targeted, out of field response." (PMID 26317641, 2015). "To assess their role in cerebellar and medulloblastoma (MB) development, we deleted the miR-17∼92 cluster family in Nestin-positive neural progenitors and in mice heterozygous for the Sonic Hedgehog (SHH) receptor Patched 1 (Ptch1+/−)." (PMID 24928431, 2014). "Because eRMS is one of the three major tumor types that develop in Ptch1+/− mutant mice and the other two tumor types (BCC and medulloblastoma) have shown response to SMO inhibition in vivo, it was assumed that targeting the Hedgehog pathway would have utility in eRMS." (PMID 22619564, 2012). "In our study, we have silenced expression of GLI1 using a small interfering RNA (siRNA), followed by the determination of gene expression patterns of PTCH1, Cyclin D2, Plakoglobin, NKX2.2 and PAX6 in 14 cell lines and 41 primary medulloblastoma and astrocytoma tumor samples." (PMID 21059263, 2010). "PTCH1 promoter methylation was less frequently observed than Cyclin D2 promoter methylation in astrocytomas, and not at all in medulloblastomas." (PMID 21059263, 2010). "Several mutations of the PTCH1 gene have been identified in patients with NBCCS, and, in those with BCCs and medulloblastomas that are apparently not hereditary." (PMID 19032739, 2008). "Similarly, ATM, NBN, PALB2, PMS2, PTCH1, and SUFU are tumor suppressor and germline risk genes for medulloblastoma, but CH variants in these genes have not been found in prior studies." (PMID 32508881, 2020). "However, while SmoA1 and Ptch1-KO animal models are both characterized by highly penetrant medulloblastoma development, the phenotypes of the two do not fully overlap." (PMID 31873117, 2019).